BAP1 (BRCA1 associated deubiquitinase 1)
Diseases named in the same sentence as BAP1 in open-access papers (continued):
Sharing a sentence is not in itself a finding about the gene and the disease.
colon carcinoma (continued). "A recently identified BAP1 inhibitor, TG2-179-1, which seems to covalently bind to the active site of BAP1, exhibits potent cytotoxic activity against colon cancer cells, with half-maximal inhibitory concentrations of less than 10 μM, and inhibits colon tumor growth." (PMID 36754982, 2023). "The upregulation of BAP1 in colon cancer led us to investigate whether BAP1 regulates the viability of colon cancer cells." (PMID 36754982, 2023). "To determine the status of BAP1 expression in colon cancer, we searched several online databases." (PMID 36754982, 2023). "BAP1 depletion inhibits the growth of colon tumors in xenograft mice." (PMID 36754982, 2023). "Notably, TG2-179-1 also killed CCD-18Co and CCD-112CoN normal colon cells, which express BAP1 at very low levels, with cytotoxic activity comparable to that of colon cancer cells." (PMID 36754982, 2023). "The observation that TG2-179-1 still killed BAP1-insensitive colon cancer cells (HCT15 and LoVo) raised the question of whether TG2-179-1 exerts its cytotoxic activity by targeting BAP1." (PMID 36754982, 2023). "Therefore, the activity of BAP1 to support the viability of these colon cancer cells is specific and dependent on its DUB activity." (PMID 36754982, 2023). "Collectively, these data indicate that BAP1 is upregulated in colon cancer." (PMID 36754982, 2023). "Second, BAP1 depletion renders colon cancer cells less sensitive to TG2-179-1." (PMID 36754982, 2023). "Therefore, it is unlikely that BAP1 contributes to the survival and proliferation of colon cancer cells via the Apc/β-catenin pathway." (PMID 36754982, 2023). "Given the critical role of BAP1 in DNA replication and the survival of colon cancer cells, we performed a xenograft experiment in mice to determine whether BAP1 is required for the growth of colon cancer cells into tumors." (PMID 36754982, 2023). "Then, we tested if these genes are also highly correlated with BAP1 in UM and colon cancer." (PMID 30716094, 2019). "In the present study, we investigated whether BAP1 functions oncogenically in colon cancer." (PMID 36754982, 2023). "Finally, TG2-179-1 treatment, similar to BAP1 depletion, inhibits colon tumor growth in mice." (PMID 36754982, 2023). "Additionally, we investigated the expression level of BAP1 in colon cancer." (PMID 30716094, 2019). "Furthermore, in the colon cancer cell line MC38, deletion of BAP1 results in decreased expression of PD-L1." (PMID 39350280, 2024). "TG2-179-1 reduced the viability of all eight colon cancer cell lines in a dose-dependent manner regardless of their sensitivity to BAP1 depletion." (PMID 36754982, 2023). "The ability of BAP1 to promote colon cancer cell proliferation, however, seems to be independent of this mechanism, since BAP1 depletion did not affect the levels of β-catenin and Axin." (PMID 36754982, 2023). "The IC50 values of TG2-179-1 were less than 10 μM in all colon cancer cells, revealing no clear correlation with the requirement of BAP1 for survival." (PMID 36754982, 2023). "While HCT116, SW48 and RKO cells harbor wild-type Apc, the remaining five tested cell lines carry inactivating mutations in Apc, indicating that the requirement of BAP1 for the viability of colon cancer cells is not clearly correlated with the activity of Apc." (PMID 36754982, 2023). "MGPT was performed after her colon cancer had negative IHC staining for MSH6, and confirmed a germline mutation in MSH6, while revealing additional mutations in BAP1 and RECQL4 genes." (PMID 33541411, 2021). "This figure indicates that the expression level of BAP1 in patients with colon cancer is not correlated with vital status or gender." (PMID 30716094, 2019). "The BAP1 inhibitor TG2-179-1, which inhibits the DUB activity of BAP1 possibly by binding covalently to the active site, exhibits potent cytotoxic activity against colon cancer cells, with IC50 values of less than 10 μM, and inhibits the growth of colon tumors in xenograft mice." (PMID 36754982, 2023).
glioma (8 papers, 2017 to 2025). A benign or malignant brain and spinal cord tumor that arises from glial cells (astrocytes, oligodendrocytes, ependymal cells). "The study provides supporting evidence for the presence of Aβ in GBM and highlights the potential of BBG and BAP-1 as candidate fluorescent probes for glioma detection." (PMID 41226489, 2025). "BAP-1 likewise demonstrated exceptional glioma selectivity: thirty minutes post-injection, tumor fluorescence exceeded background by more than 2400-fold in PFA-fixed 15 μm slices and ~85-fold in live 300 μm slices." (PMID 41226489, 2025). "This indicates a high concentration of BAP-1 within glioma cells relative to adjacent normal brain tissue." (PMID 41226489, 2025). "The findings demonstrate that both BBG and BAP-1 selectively stain gliomas, providing a clear contrast from normal brain tissue." (PMID 41226489, 2025). "Direct measurements are necessary to assess the boron load per glioma cell and to determine the biological efficacy of BAP-1 in BNCT, which also depends on the neutron flux (neutrons per second per square meter)." (PMID 41226489, 2025). "Thirty minutes after intraperitoneal injection, both BBG and BAP-1 produced rapid, high-contrast labeling of glioma cells in the C57Bl/6-GL261 and -KR158 mouse models." (PMID 41226489, 2025). "The stained glioma cells emitted fluorescence near 650 nm, consistent with previously reported BAP-1 labeling of cerebral beta-amyloid plaques." (PMID 41226489, 2025). "BAP-1 fluorescence highlighted tumor cells in both glioma models, with more intense accumulation in GL261 tumors compared to KR158." (PMID 41226489, 2025). "In glioma cells, BAP1 is localised in both the nucleus and cytoplasm." (PMID 39866010, 2025). "Results showed that only the expression of BAP1 was similar among different grades of gliomas." (PMID 33330074, 2020). "Our finding that single‐pattern cytoplasmic BAP1 is associated with improved survival of patients with non‐epithelioid MPM suggests that BAP1 IHC may also be useful as a prognostic biomarker, as has been suggested for glioma." (PMID 32944962, 2021).
osteosarcoma (8 papers, 2015 to 2024). A usually aggressive malignant bone-forming mesenchymal neoplasm, predominantly affecting adolescents and young adults. "BRCA1-associated protein-1 (BAP1) is a nuclear-localized deubiquitinase, expressed at low levels in osteosarcoma tissues and cells." (PMID 39062505, 2024). "This study aims to screen out differentially expressed genes (DEGs) regulated by BRCA1-associated protein 1 (BAP1) in osteosarcoma cells, and to analyze their biological functions." (PMID 36003792, 2022). "The underlying molecular mechanisms directly mediated by BAP1 in osteosarcoma need to be further explored." (PMID 36003792, 2022). "Molecules such as UBE2T, E3 ubiquitin ligase adaptor SPOP, USP9X, USP22, and BAP1 are involved in regulating the proliferation, migration, and invasion of osteosarcoma cells through modulation of the PI3K/Akt signaling pathway." (PMID 39062505, 2024). "BAP1 inhibits the proliferation, migration, and invasion of osteosarcoma cells by negatively regulating the PI3K/Akt signaling pathway." (PMID 39062505, 2024). "In the osteosarcoma dataset of TARGET database, although BAP1 expression was similar in osteosarcoma tissues from patients with different clinicopathologic characteristics, it was positively correlated with BRCA1, CDC6, and CDC45." (PMID 36003792, 2022). "The microarray dataset GSE23035 of BAP1-knockdown osteosarcoma cells was obtained from Gene Expression Omnibus (GEO) database, consisting of shControl, shBAP1#1 and shBAP1#2 samples." (PMID 36003792, 2022). "In summary, through bioinformatics and in vitro assays, this study demonstrated that BAP1 was a tumor suppressor in osteosarcoma and provided new clues for osteosarcoma treatment such as BAP1-targeted therapy." (PMID 36003792, 2022). "The DEGs between the BAP1-knockdown osteosarcoma cells and the untreated osteosarcoma cells were screened with limma package, and then subjected to Gene Ontology (GO) and Kyoto Encyclopedia of Genes and Genomes (KEGG) enrichment analysis." (PMID 36003792, 2022). "In this study, we obtained the osteosarcoma dataset from the Therapeutically Applicable Research to Generate Effective Treatments (TARGET) database and the BAP1 knockdown dataset GSE23035 associated with osteosarcoma from the gene expression omnibus (GEO) database." (PMID 36003792, 2022). "However, Pearson analysis demonstrated that BAP1 was negatively correlated with the fraction of naïve CD4 T cells in osteosarcoma tissues." (PMID 36003792, 2022). "In this study, the roles of BAP1 in potential targets, biological functions, signaling pathways, and immune infiltration were comprehensively explored by mining the osteosarcoma datasets from GEO and TARGET databases using the rapidly developing bioinformatics in recent years." (PMID 36003792, 2022). "In contrast to the BAP1 mutation, PBRM1 mutation was primarily associated with ATAC-peaks exhibiting increased accessibility, suggesting PBRM1 may have a role in gene silencing, consistent with a previous report using osteosarcoma cells." (PMID 36973268, 2023). "Interestingly, focal adhesion was enriched in shBAP1#1 and shBAP1#2 samples, suggesting BAP1 might inhibit EMT in osteosarcoma." (PMID 36003792, 2022). "BAP1 might be a tumor suppressor in osteosarcoma and a promising therapeutic target." (PMID 36003792, 2022). "In vitro, BAP1 could inhibit osteosarcoma cells proliferation and EMT." (PMID 36003792, 2022). "However, the roles of BAP1 in osteosarcoma are currently unknown." (PMID 36003792, 2022). "To confirm the role of BAP1 in GSE23035, we performed GSVA analysis in the osteosarcoma dataset in TARGET database." (PMID 36003792, 2022). "However, we could not find any osteosarcoma dataset about BAP1 mutation, so the potential mechanisms involved in the progression of osteosarcoma are to be explored later." (PMID 36003792, 2022). "In BAP1-overexpression SJSA1 cells, the opposite results displayed, implying BAP1 could inhibit osteosarcoma cell growth and EMT." (PMID 36003792, 2022).
osteosarcoma (continued). "To further validate anti-cancer effects of BAP1, we first detected BAP1 expression in nontumor osteoblast cell line hFOB1.19 and osteosarcoma cell lines SAOS2 and SJSA1." (PMID 36003792, 2022). "In this study, by analyzing osteosarcoma dataset GSE23035 in GEO database, we found that BAP1 could significantly regulate 139 genes expression." (PMID 36003792, 2022). "BAP1 is known to regulate migration, epithelial to mesenchymal transition (EMT) and therefore metastasis in various cancers including cervical cancer, breast, osteosarcoma and kidney." (PMID 33240524, 2020).
Pleural effusion (8 papers, 2016 to 2026). The presence of an excessive amount of fluid in the pleural cavity. "The introduction of BAP1, MTAP and p16 tests has greatly improved the diagnostic accuracy of pleural effusions, but it is necessary to perform at least two of these tests (i.e., BAP1 and MTAP) to reach a good sensitivity." (PMID 38067238, 2023). "Specifically, FISH analysis of pleural effusion, which contains a high number of normal cells, revealed that BAP1 biallelic loss was 24%, while the same analysis of FFPE showed that the loss was 73%." (PMID 35885614, 2022). "Accordingly, MLPA on DNA extracted from fresh pleural effusion specimens showed a 50% loss of the entire BAP1 gene, which was again consistent with the complete loss of the wt sequence." (PMID 35885614, 2022). "In this prospective cohort, we also confirmed the usefulness of BAP1 and MTAP IHC tests on pleural effusions, whose combination reached excellent diagnostic accuracy." (PMID 38067238, 2023). "This is consistent with MLPA analysis of the proband’s pleural effusion, showing a 50% deletion of BAP1." (PMID 35885614, 2022). "Of this cohort, 6 BAP1-positive patients and 11 BAP1-negative patients had pleural effusion supernatant available for analysis." (PMID 29085180, 2017). "VEGFA prognostic data was utilised in this study for two reasons: firstly, it is a previously established adverse prognostic marker when elevated in pleural effusion, and secondly, it is used to investigate the possible functional relationship between BAP1 and VEGFA." (PMID 29085180, 2017). "More recently, neutrophil to lymphocyte ratios, serum inflammatory markers, as well as serum, tissue and pleural effusion Vascular endothelial growth factor (VEGF) levels and and BRCA1-Associated Protein 1 (BAP1) mutation BAP1 status have been related to outcomes among MM patients." (PMID 27376267, 2016). "To further investigate prognostic implications within our cohort and investigate the potential role of BAP1 in regulating VEGFA levels, we explored pleural effusion VEGFA protein concentrations." (PMID 29085180, 2017).
small cell lung carcinoma (8 papers, 2020 to 2025). Small cell lung cancer (SCLC) is a highly aggressive malignant neoplasm, accounting for 10-15% of lung cancer cases, characterized byrapid growth, and early metastasis. "In BAP1-dependent human cancers, such as small cell lung cancer (SCLC), MBD6 tends to be a part of the predominant complex formed." (PMID 36180891, 2022). "However, it was found that the small cell lung cancer (SCLC) cells with depleted BAP1 was resistant to iBAP-II." (PMID 37543638, 2023). "Moreover, we have recently characterized a human small cell lung cancer (SCLC)-specific epigenetic axis comprised of BAP1/ASXL3/BRD4." (PMID 36180891, 2022). "In addition, the ET domain–binding motif, which shares similar amino acid sequences from other BRD4-ET–binding proteins such as CHD4 and NSD2/3, also mediates interaction of BRD4-ET with ASXL3 and functionally links BRD4 to the BAP1 complex in a small-cell lung cancer (SCLC) subtype." (PMID 34540900, 2021). "Intriguingly, ASXL3, similar to ASXL1 and ASXL2, forms a PR-DUB complex with BAP1 but also exclusively interacts with BRD4, which binds to acetylated histones via its bromodomains in small cell lung carcinoma." (PMID 38791157, 2024). "A study demonstrated that ASXL3 forms an oncogenic axis with BRD4 and BAP1, activating ASCL1/MYCL/E2F signaling in small cell lung cancer." (PMID 38791157, 2024). "In small cell lung carcinoma (SCLC), BAP1 promotes oncogenic roles inducing the expression of ASCL1 (Achaete-Scute Family BHLH Transcription Factor 1), a key lineage-specific oncogenic driver in SCLC." (PMID 36318367, 2022).
biliary tract cancer (7 papers, 2015 to 2026). "DDR genes such as breast cancer susceptibility gene 1/2 (BRCA 1/2), ataxia-telangiectasia mutated (ATM), and BRCA1-associated protein 1 (BAP1) were identified germline or somatic inactivation in 63.5% biliary tract cancer patients." (PMID 36226174, 2022). "Interesting, BAP1 mutant CCAOs showed enhanced sensitivity to sorafenib, a multikinase inhibitor commonly used in biliary tract cancer." (PMID 41797921, 2026).
lymphoma (7 papers, 2015 to 2025). A malignant (clonal) proliferation of B- lymphocytes or T- lymphocytes which involves the lymph nodes, bone marrow and/or extranodal sites. "Nevertheless, cases of non-Hodgkin lymphoma have been reported in carriers of germline BAP1 mutations, and lymphomas with other genetic aberrations were shown to acquire BAP1 gene silencing via epigenetic mechanisms." (PMID 38529289, 2024). "While BAP1 is a highly important tumor suppressor, lymphomas are not among the major cancer types associated with germline or acquired BAP1 mutations, and our current study didn’t directly address the role of BAP1 in lymphomagenesis." (PMID 38529289, 2024). "Furthermore, lymphomas that carry other genetic aberrations have been shown to acquire BAP1 gene silencing via epigenetic mechanisms." (PMID 33912157, 2021). "Notably, we discovered that BAP1 tends to function as a tumor suppressor in hot tumors with high MHC-II expression, such as lymphoma, blood cancer, and skin cancers." (PMID 39817454, 2025). "It has been reported that BAP1 is recruited to the sites of DNA damage to promote DNA repair and that chicken lymphoma DT40 cells lacking BAP1 are more sensitive to ionizing radiation." (PMID 30669483, 2019). "BAP1 and WDR9 are novel chromatin modifiers which associations with malignant lymphoma have not been reported." (PMID 28152507, 2017).
melanocytic neoplasm (7 papers, 2017 to 2025). "Recently, a novel germline BAP1 mutation (c.1777C > T) has been described in a family whose members were affected by early‐onset melanocytic neoplasms but also developed other types of cancer including thyroid papillary cancer." (PMID 36873079, 2023). "BAP1 gene absence exacerbates the phenotype of PC loss in melanocytic neoplasms, while BAP1 loss is found in nearly half of cases of MPM." (PMID 37542187, 2023). "Family members carrying the germline BAP1 mutation c.1777C>T, which produces a truncated BAP1 protein product, showed early-onset melanocytic neoplasms and other neoplasia, including thyroid cancer." (PMID 36077430, 2022). "Wiesner and colleagues demonstrated that BAP1 assessment by IHC (immunohistochemistry) was a useful tool for subtyping melanocytic neoplasms." (PMID 28404968, 2017). "Some authors have classified these sporadic tumors into the heterogeneous of umbrella of atypical Spitz tumors, given that spitzoid melanocytic neoplasms can display immunohistochemical BAP1 staining that may be positive, negative, or only perinuclear with absent nuclear staining." (PMID 29166932, 2017).
skin cancer (7 papers, 2020 to 2025). "Various risk factors in SPCs associated with breast and skin cancers include age, gender, socio-cultural factors, radiotherapy, chemotherapy, and mutations in BRCAs, CDKN2A, VDK4, and BAP1." (PMID 39917137, 2025).
spitz nevus (7 papers, 2012 to 2021). A benign, acquired or congenital, usually single skin lesion. "Instead, the tumors found in these BAP1 mutated patients show large epithelioid clonal cells (that resemble those found in Spitz nevus and in ASTs) but these cells are present only in the dermis (there is no epidermal component)." (PMID 22935333, 2012). "A final diagnosis of atypical Spitz nevus with BAP1 loss was rendered." (PMID 35052351, 2021). "The second novel variant, c.1777dupC, which is predicted to cause a truncated protein after 50 amino acids, was found in a young patient diagnosed with an atypical Spitz nevus/tumor with loss of BAP1 expression and with a second-degree relative deceased owing to RCC at the age of 46." (PMID 32325837, 2020). "Interestingly, loss of BAP1 in an unusual cutaneous tumor, the atypical Spitz nevus, was associated with a higher presence of T cells." (PMID 28391358, 2017). "However, positive BRAFV600E expression in many BAP1 negative lesions, as well as a lack of epidermal hyperplasia, clefting between melanocytes, and Kamino bodies, sets this population apart from traditional Spitz nevi." (PMID 29166932, 2017).
squamous cell carcinoma (7 papers, 2016 to 2023). A carcinoma arising from squamous epithelial cells. "Subset analyses of 327 squamous cell carcinomas and 86 non-squamous cell carcinomas revealed previously unreported SMGs in BAP1 and IL28A, respectively." (PMID 34620846, 2021).